COL2A1 (collagen type II alpha 1 chain)
Diseases named in the same sentence as COL2A1 in open-access papers (continued):
Sharing a sentence is not in itself a finding about the gene and the disease.
collagenopathies (8 papers, 2014 to 2025). "Our data add new variants to the repertoire of COL2A1 mutation resulting in related collagenopathies." (PMID 24949742, 2014). "Bilateral RRD was only seen in collagenopathies/vitreoretinopathies with COL2A1 (n = 2, 33.3%), COL11A1 (n = 1, 16.7%), COL18A1 (n = 1, 16.7%) and FBN1 (n = 2, 33.3%) genotypes." (PMID 41465105, 2025). "If collagenopathies (COL2A1, COL11A1, COL18A1) and Marfan syndrome are removed, this figure (n = 3/401, 0.7%) remains 70× the population risk." (PMID 41465105, 2025). "The collagens with the strongest known disease association are COL2A1 and COL7A1, with 19 and 13 implicated collagenopathies, respectively." (PMID 37189830, 2023). "Pathogenic variants for collagenopathy were uncovered in 10/12 children: COL11A1 (heterozygous) in six, COL2A1 (heterozygous) in two, and COL9A1 (homozygous) in two." (PMID 33951325, 2021).
disc degeneration (7 papers, 2016 to 2025). "During the process of IDD, the gene expression of AG, BG, and collagen (Col)2A1 were decreased, whereas the expression of Col1A2 was increased, which confirmed disc degeneration." (PMID 28149534, 2017). "Lastly, the TGF‐β‐induced activation of the CTGF secretory pathway in Smurf2‐expressing disc cells, a potential mechanism for disc degeneration in Col2a1‐Smurf2 transgenic mice, could also be a mechanism for disc aging/degeneration in WT mice and humans." (PMID 30828686, 2019). "Reduced GAGs and COL2A1 lead to reduced hydration, impairing the ability of the CEP to withstand loading and transport essential nutrients, rendering it more susceptible to cracks or fissures that bring inflammation, blood vessel and nerve ingrowth, and painful disc degeneration." (PMID 40328789, 2025). "There is also a report that COL2A1 rs2276454 polymorphism is associated with an increased risk, and COL2A1 rs1793953 might be a protective factor of developing disc degeneration in a Chinese Han population, however these SNPs are not validated in other ethnic populations." (PMID 33543030, 2020). "Histological examinations and aggrecan, Col1A1, Col2A1 and matrix metalloprotease (MMP)-3 mRNA expression confirmed the disc degeneration, supporting the imaging results." (PMID 26924131, 2016).
scoliosis (7 papers, 2014 to 2025). A congenital or acquired spinal deformity characterized by lateral curvature of the spine. "During the initiation of scoliosis (P20), we observed wedging of IVDs close to the apex of the curvature in Col2a1-Cre; Adgrg6f/f mice with scoliosis, associated with a shift of the nucleus pulposus towards the convexity of the curve." (PMID 34318745, 2021). "To determine if similar morphological changes of the spine were associated with the initiation and progression of scoliosis, we harvested the thoracic spine (T5–T12) of Col2a1-Cre; Adgrg6f/f and control littermates at P20 and P120." (PMID 34318745, 2021). "Altogether, this suggested that loss of Adgrg6 in committed cartilages of the axial skeletal is sufficient to generate a mild susceptibility to scoliosis, although with a much lower penetrance compared with removal of Adgrg6 in the whole spine (i.e., Col2a1-Cre; Adgrg6f/f)." (PMID 34318745, 2021). "The lower penetrance of scoliosis in Col2a1-CreERT2; Adgrg6f/f mice was comparable with the results observed in the ATC; Adgrg6f/f mice induced from P1–P20." (PMID 34318745, 2021). "We observed regular expression of COLII in the IVDs at P20 regardless of genotype; however, the typical distribution of COLI-positive (COLI+) cells was altered Col2a1-Cre; Adgrg6f/f mice with scoliosis." (PMID 34318745, 2021). "Scx-Cre; Adgrg6f/f mutant mice—targeting recombination only in dense connective tissues—displayed a high penetrance of scoliosis comparable with that observed in Col2a1-Cre; Adgrg6f/f mice." (PMID 34318745, 2021). "To determine the natural history of scoliosis in Col2a1-Cre; Adgrg6f/f mice, we performed longitudinal X-ray analysis at postnatal day 10 (P10) out to P120." (PMID 34318745, 2021). "Notably, both conditional PIEZO1 knockout models (Col2a1-CreERT; Piezo1flox/flox) and pharmacological blockade significantly decelerate scoliosis progression." (PMID 40714837, 2025). "Except for those two patients with the COL2A1 mutation who developed scoliosis after initiating treatment, no exacerbation of scoliosis or other skeletal deformities was observed in the remaining patients." (PMID 35250876, 2022). "To examine whether alterations could further explain scoliosis in Col2a1-Cre; Adgrg6f/f mice in bone quality, we generated Bglap-Cre; Adgrg6f/f mice." (PMID 34318745, 2021). "(E–H’) Longitudinal X-ray analysis of a representative Col2a1-Cre; Adgrg6f/f mutant mouse at P10 (E, E’), P20 (F, F’), P40 (G, G’), and P120 (H, H’), showing adolescent-onset (F) and progressive (F–H) thoracic scoliosis, with the apex of scoliosis indicated (red arrows; F–H’)." (PMID 34318745, 2021). "We did not observe scoliosis in Col2a1-CreERT2; Adgrg6f/f mutant mice after perinatal induction (P1–P5) at P30 (0.0%; n = 8) (C’)." (PMID 34318745, 2021). "Furthermore, IHC showed reduced pCREB expression in the nucleus pulposus in Col2a1-Cre; Adgrg6f/f mutants at P10 (H’), suggesting that alteration of CREB signaling emerges before the initiation of scoliosis." (PMID 34318745, 2021).
Arthritis (6 papers, 2012 to 2025). Inflammation of a joint. "Systemic elucidation of functional crosstalk between the cis- and trans-acting elements involved in Col2a1 regulation can lead to development of therapeutic interventions for arthritis and other cartilage degenerative diseases." (PMID 22815835, 2012). "Col2a1 and aggrecan are the main components of ECM, and their destruction plays a crucial role in the onset and progression of early arthritis." (PMID 40746264, 2025). "The primary symptom of early arthritis is believed to be a decline in ACAN According to our findings, PN prevented the breakdown of the ECM by stopping the deterioration of COL2A1 and ACAN." (PMID 37569659, 2023).
deafness (6 papers, 2012 to 2025). An inherited or acquired condition characterized by the complete loss of the ability to hear from one or both ears. "COL2A1 gene variations can result in syndromic eoHM, associated with eye connective tissue, vitreous degeneration, deafness, joint problems, and facial abnormalities due to the production of type II collagen." (PMID 38517428, 2024).
dwarfism (6 papers, 2021 to 2025). "Heterozygous variants in COL2A1 are frequently associated with a range of dwarfism and skeletal dysmorphic disorders." (PMID 40567897, 2025). "Heterozygous mutations in the COL2A1 gene are often associated with a spectrum of dwarfism and skeletal malformations." (PMID 37726736, 2023). "Heterozygous COL2A1 mutations are usually associates with a spectrum of dwarfism and skeletal malformation diseases." (PMID 34567078, 2021). "For example, in the Dwarf Lop breed, we identified a strong signature of selection in the region of the COL2A1 gene, which is known to be involved in a broad spectrum of skeletal defects, including dwarfism." (PMID 35062866, 2022). "Other regions included novel candidate genes that might contribute to the phenotypic variation among the analyzed breeds, including genes for pigmentation-related traits (EDNRA, EDNRB, MITF and OCA2) and body size, with a strong candidate for dwarfism in rabbit (COL2A1)." (PMID 35062866, 2022).
melanoma (6 papers, 2010 to 2025). A malignant, usually aggressive tumor composed of atypical, neoplastic melanocytes. "COL2A1 and GPR112 have high mutation rates in melanoma, but their roles differ in other types of carcinomas." (PMID 33203961, 2020). "From the microarray results, the three genes (α-2-macroglobulin (A2M), collagen type II alpha-1 (Col2A1), melanoma inhibitory activity-1 (MIA)) showing the highest upregulation or fold change were selected for validation by means of RT-PCR." (PMID 20579363, 2010). "Moreover, the presence of the COL2A1 protein in human melanoma tumor sections will be validated in the future." (PMID 32962144, 2020). "Additionally, expression of the prominent cartilage matrix proteins type 2 collagen (Col2a1), Aggrecan (Acan), and melanoma inhibitory activity/cartilage-derived retinoic acid-sensitive protein (MIA/CD-RAP) was analyzed." (PMID 26273614, 2015).
glaucoma (5 papers, 2008 to 2025). Increased pressure in the eyeball due to obstruction of the outflow of aqueous humor. "Glaucoma was present in five (5/42, 12%) probands, all of whom had COL2A1 mutations." (PMID 32756486, 2020). "Details of glaucoma medications were not available but only two patients (BEST1, COL2A1) required surgical management (tube shunt)." (PMID 41465105, 2025).
ovarian carcinoma (5 papers, 2017 to 2022). A malignant neoplasm originating from the surface ovarian epithelium. "ECM-receptor interaction was enriched based on the KEGG pathway in our study, while COL3A1, COL5A2, and COL2A1 were regarded as potential ECM components associated with cytostatic drug resistance in ovarian cancer cells." (PMID 28562334, 2017). "Expression profiles of COL2A1 and COL1A2 were independent predictors of survival in ovarian cancer and head and neck cancer respectively." (PMID 28410203, 2017).
chordoma (4 papers, 2010 to 2025). Chordomas are rare malignant tumors arising from embryonic remnants of the notochord in axial skeleton. "COL2A1 was also shown to be down-regulated by TBXT expression in a clival chordoma cell line (UM-Chor1)." (PMID 34070849, 2021). "Interestingly, Col2a1-null mice lack intervertebral discs and cannot remove the notochord, suggesting the potential importance of this gene in chordoma development." (PMID 34070849, 2021). "Interestingly, we observed the persistent expression of ntla and col2a1a, the zebrafish homologs of the human T gene and COL2A1 respectively, which are specifically up-regulated in chordoma." (PMID 25071022, 2014). "In addition, we found a significant up-regulation of two homologs of chordoma markers, ntla (T) and col2a1a (COL2A1)." (PMID 25071022, 2014). "Indeed, in a recent study other genes were found differentially expressed in both chordomas and related cell lines, among them the α1 collagen type II (COL2A1) was significantly over-expressed." (PMID 25071022, 2014). "Interestingly, we also observed the maintenance of the expression of ntla and col2a1a, the zebrafish homologs of the human T gene and COL2A1, which were found to be specifically up-regulated in chordoma." (PMID 25071022, 2014).
dysplasia (4 papers, 2015 to 2025). A usually neoplastic transformation of the cell, associated with altered architectural tissue patterns. "In the present study, ten Chinese families with COL2A1 mutations were classified into five categories of dysplasia, including SEDC, OSCDP, Czech dysplasia, Kniest dysplasia and EDMMD." (PMID 32071555, 2020). "We believe the results from the present study would help improve our understanding of COL2A1-associated dysplasia, especially in Chinese population." (PMID 32071555, 2020). "Our aim is to characterize the clinical and molecular phenotypes of Chinese patients with COL2A1-related dysplasia and to explore their phenotype-genotype relations." (PMID 32071555, 2020). "Clinical data were collected, physical examinations were conducted, and X-ray radiography and genetic analyses were performed in ten families involving 29 patients with COL2A1-related dysplasia." (PMID 32071555, 2020). "The cartilage matrix proteoglycan and Col2a1 content was significantly lower, suggesting fetal articular cartilage dysplasia." (PMID 26434683, 2015). "Although a large number of COL2A1 mutations have been reported and the phenotype-genotype relations in COL2A1-related dysplasia have been partially elucidated, the clinical and molecular characteristics in Chinese patients with COL2A1-related dysplasia remain unclear." (PMID 32071555, 2020).
intervertebral disc degeneration (4 papers, 2018 to 2024). "We have recently demonstrated that overexpression of Smurf2 under the control of type II collagen alpha 1 (Col2a1) promoter induces an intervertebral disc degeneration phenotype in Col2a1‐Smurf2 transgenic mice." (PMID 30828686, 2019). "Moreover, conditional knockout of Piezo1 (Col2a1-CreERT Piezo1flox/flox) attenuated the mechanical injury-induced intervertebral disc degeneration (IVDD)." (PMID 38553442, 2024).
joint disease (4 papers, 2012 to 2024). "Given that OA is a systemic joint disease, an analysis was conducted on both the articular cartilage of the hip joint in Cbfbf/f;Col2a1-CreERT mice and the articular cartilage of the knee joint in Cbfbf/f;Acan-CreERT mice." (PMID 38805545, 2024). "However it is notable that CILP2, like other high-scoring plasma protein markers such as COMP, TNXB, THBS4, SPP1, COL2A1 to name a few, are associated with connective tissue development (cartilage matrix synthesis in the case of CILP2) and bone and joint disorders." (PMID 22558154, 2012).
Obesity (4 papers, 2012 to 2022). Accumulation of substantial excess body fat. "In addition, one patient (P.6) with COL2A1 mutation showed unexpected obesity and severe skeletal deformities and arthrogryposis, suggesting that weight gain and obesity may also be major concerns of epiphyseal dysplasia and contribute to the morbidity associated with joint problems." (PMID 35250876, 2022). "Since we found that SREBP-2 was associated with BMI and as obesity is characterized by upregulated cholesterol synthesis we evaluated the effect of sterols on SREBP-2 expression and chondrocytes markers such as MMP-13 and COL2A1." (PMID 22662110, 2012).
Osteochondroma (4 papers, 2015 to 2025). A common, benign cartiliginous neoplasm arising from the metaphysis of bone. "Other possibilities are that osteochondroma-forming cells are derived from the groove of Ranvier, or else the periosteum or perichondrium, which showed Cre recombinase activity in the collagen type II α1 (Col2a1)-CreERT2 mice used in this study." (PMID 26091072, 2015).
tendinopathy (4 papers, 2017 to 2021). "Compared to the negative control group, overexpressing miR-337-3p significantly reduced the expression of chondro-osteogenic markers Spp1 and Col2a1 in patellar tendon of tendinopathy model." (PMID 31065679, 2020). "In contrast to previous equine and sheep models of tendinopathy, typical chondroid gene expression changes (including increased expression for ACAN and COL2A1) were not apparent in the present study." (PMID 29023489, 2017). "However, in contrast to previous equine and ovine models of tendinopathy, increases in GAG content (proteoglycan scores) or increased gene expression of ACAN and COL2A1 were not apparent in the DDFT." (PMID 31013317, 2019).
atherosclerosis (3 papers, 2017 to 2023). A disease characterized by the build-up of fatty material and calcium deposition in the arterial wall resulting in partial or complete occlusion of the arterial lumen. "CEBPD and RUNX1 were identified as the key regulators for both atherosclerosis-associated cell states despite the higher expression of Cebpd in Vcam1+ SMCs and Runx1 in Col2a1+ SMCs." (PMID 37060905, 2023). "Comparison of top-scored IPA canonical analysis showed that atherosclerosis signaling may relate to interactions between CLU and proteins encoded by congenital toxoplasmosis susceptibility genes (TGFβ1, COL2A1, ALOX12, NFκB1)." (PMID 28904337, 2017). "Importantly, the genetic variation in the Vcam1+ SMCs and Col2a1+ SMCs contributed to CAD heritability beyond other cell states, suggesting that these cell states are particularly important in understanding the pathobiology of atherosclerosis." (PMID 37060905, 2023).
Epiphyseal dysplasia (3 papers, 2014 to 2022). "A novel COL2A1 mutation (c.1744G>A (p.Gly582Ser)) was identified within one Japanese family with epiphyseal dysplasia." (PMID 25124518, 2014). "Recently, inheritable epiphyseal dysplasia caused by novel COL2A1 mutations has been linked to three inherited diseases of the hip joint." (PMID 25124518, 2014). "Based on these findings, haplotype analysis of her and her family members was performed by examining select candidate genes from the critical interval for epiphyseal dysplasia of the femoral head on 12q13 and sequencing the promoter and exonic regions of COL2A1." (PMID 25124518, 2014).
glioma (3 papers, 2015 to 2017). A benign or malignant brain and spinal cord tumor that arises from glial cells (astrocytes, oligodendrocytes, ependymal cells). "The introduction of an IDH2 R172K mutation, the main IDH2 mutation in gliomas, into C3H10T1/2 was previously shown to reduce the expression of the COL2A1 gene and gave rise to poorly differentiated sarcomas in xenograft models." (PMID 26161668, 2015).
leukaemia (3 papers, 2021 to 2024). "In addition, we also found some leukaemia‐specific proteins, oncogenes (COL2A1, CLIP1, NUMA1 and GALK1), and stem cell‐regulated proteins (ACAN, VCAN, COMP and PRDX6)." (PMID 38499475, 2024).
Marshall syndrome (3 papers, 2017 to 2025). "A short nose, anteverted nares, midfacial hypoplasia, and a flat nasal bridge are common in patients with Marshall syndrome and are also seen in young patients with mutations in the COL2A1 gene (STL1)." (PMID 28841907, 2017).
osteosarcoma (3 papers, 2015 to 2022). A usually aggressive malignant bone-forming mesenchymal neoplasm, predominantly affecting adolescents and young adults. "For example, just 2/12 Col2a1-Cre; Ptenfl/fl mice developed OS, and likewise, we observed only one osteosarcoma formation from 17 Osx1-Cre; Ptenfl/fl mice aged to 18 months." (PMID 26317218, 2015).
renal fibrosis (3 papers, 2015 to 2025). A final common manifestation of a wide variety of chronic kidney diseases characterized by glomerulosclerosis and tubulointerstitial fibrosis. "It has been reported that miR-29b suppresses progression of renal fibrosis by down-regulating tropomyosin 1 and COL2A1." (PMID 25356754, 2015). "To unravel the physiological roles of PPM1K in renal fibrosis, we analyzed the RNA-sequencing dataset of a PPM1K-overexpressing HK2 cell line (GSE212681) and identified reduced expression of fibrosis-related genes such as Col1A1, Col2A1, CTGF, vimentin, and FN1 (Fig. EV3)." (PMID 40588562, 2025).
sarcoma (3 papers, 2015 to 2024). A usually aggressive malignant neoplasm of the soft tissue or bone. "Then, we analyzed the expression of biomarkers of osteoblasts (COL1A1, BGLAP and RUNX2), chondrocytes (COL2A1, COMP and SOX9) and sarcoma (POSTN and DCN), adipocyte (LPL and PPARG) and BMSCs." (PMID 39715773, 2024).
vitreous degeneration (3 papers, 2013 to 2024). "Furthermore, two common ocular features in COL2A1 exon 2 mutations are vitreous degeneration and radial perivascular retinal degeneration." (PMID 23592912, 2013).
achondroplasia (2 papers, 2012 to 2021). Achondroplasia is the most common form of chondrodysplasia, characterized by rhizomelia, exaggerated lumbar lordosis, brachydactyly, and macrocephaly with frontal bossing and midface hypoplasia. "Reports implicate gross structural changes in the gene encoding type II collagen (COL2A1) as the basic defect in achondroplasia." (PMID 23259098, 2012).
colon cancer (2 papers, 2014 to 2018). "mir675 is shown to up-regulate the essential cartilage matrix component COL2A1 essential in cartilage regeneration, while both H19 and mir675 are found to be upregulated in human colon cancer and primary human colorectal cancers." (PMID 24587348, 2014).